METTL3 (methyltransferase 3, N6-adenosine-methyltransferase complex catalytic subunit)
Diseases named in the same sentence as METTL3 in open-access papers (continued):
Sharing a sentence is not in itself a finding about the gene and the disease.
osteosarcoma (58 papers, 2019 to 2025). A usually aggressive malignant bone-forming mesenchymal neoplasm, predominantly affecting adolescents and young adults. "METTL3 is associated with the migration, invasion, and metastasis of osteosarcoma cells." (PMID 40176793, 2025). "The expression of METTL3 is elevated in osteosarcoma stem cells (OSCs), causing the increased m6A modifications in OSCs as compared with non‐OSCs, which may be one of the principal reasons why OS is prone to chemoresistance and metastasis." (PMID 34586737, 2021). "In osteosarcoma (OS), the m6A level for RNA methylation and the expression level of METTL3 were upregulated in human OS tissues and OS cell lines." (PMID 40136363, 2025). "On the whole, this research revealed a new function for METTL3 in anlotinib resistance in osteosarcoma, demonstrating that METTL3 enhances DNA‐PKcs expression through m6A methylation of PRKDC mRNA." (PMID 39924638, 2025). "m6A modification of OLE_LINK82PRKDC mRNA induced by METTL3 contributes to anlotinib resistance in osteosarcoma." (PMID 39924638, 2025). "In particular, METTL3 controls ATAD2 expression through m6A modification in osteosarcoma, thus boosting tumour growth, migration, and invasion." (PMID 39924638, 2025). "A recent study on osteosarcoma (OS) revealed that the inhibition of METTL3 can disrupt Wnt signaling activity by altering the m6A levels of LEF1, resulting in the suppression of proliferation, migration, and invasion in OS cells." (PMID 40136363, 2025). "The METTL3/TGF-β1 signaling axis drives osteosarcoma tumorigenesis by enhancing CAFs differentiation, offering a novel therapeutic target to combat advanced metastatic disease." (PMID 40986143, 2025). "This study summarized recent significant advancements, highlighting that METTL3 promotes osteosarcoma cell proliferation by regulating LEF1 m6A methylation and activating the WNT/β-catenin signaling pathway." (PMID 41019082, 2025). "We demonstrated that YTHDF1 knockdown decreased PRKDC mRNA and DNA‐PKcs protein levels and reversed the changes in osteosarcoma sensitivity to anlotinib induced by METTL3 overexpression." (PMID 39924638, 2025). "Our findings elucidate, for the first time, the regulation of DNA‐PKcs expression by METTL3, thereby enhancing osteosarcoma resistance to anlotinib." (PMID 39924638, 2025). "Multiple studies have revealed the pivotal role of methyltransferase‐like 3 (METTL3), an RNA methyltransferase with respect to the progression of tumours, such as osteosarcoma, bladder cancer, and glioblastoma." (PMID 39924638, 2025). "Nevertheless, current research on m6A methylation modifications in osteosarcoma has predominantly focused on METTL3, METTL14, WTAP, ALKBH5, and YTHDF2, with few studies on other m6A methylation regulators." (PMID 40176793, 2025). "Our findings confirm the significance and efficacy of targeting METTL3‐mediated m6A modification and DNA‐PKcs in overcoming drug resistance in osteosarcoma, potentially offering a novel therapeutic strategy for this challenging malignancy." (PMID 39924638, 2025). "Functionally, METTL3 enhances anlotinib resistance in osteosarcoma, which is reversed by PRKDC knockdown." (PMID 39924638, 2025). "M6A alpha Base transferase METTL3 enhances osteosarcoma progression by increasing m6A methylation of LEF1 mRNA, thereby activating the Wnt/β-catenin signaling pathway and promoting cancer cell proliferation, migration, and invasion." (PMID 39445018, 2024). "Studies have also reported that silencing METTL3 in human osteosarcoma cells significantly inhibits cell proliferation, migration, and invasion and promotes apoptosis." (PMID 38255808, 2024). "For example, methyltransferase-like 3 (METTL3) is defined as a key methylation enzyme as an m6A “writer”, and increased METTL3 expression was detected in osteosarcoma cells showing doxorubicin resistance." (PMID 38331776, 2024).
osteosarcoma (continued). "In line with this study, the expression level of METTL3 was significantly upregulated in osteosarcoma tissues and cell lines." (PMID 35860263, 2022). "For example, METTL3 can promote the progression of osteosarcoma by regulating the m6A level of LEF1." (PMID 38024481, 2022). "METTL3 promotes osteosarcoma cell progression by upregulating the m6A level of LEF1 and activating the Wnt/β-catenin signaling pathway." (PMID 33980824, 2021). "The m6A methyltransferase METTL3 promotes osteosarcoma progression by regulating the m6A level of LEF1." (PMID 33490266, 2021). "Through analyzing the prognosis information of osteosarcoma patients, METTL3, YTHDC1, and FTO were identified as significant markers associated with OS probability." (PMID 34011074, 2021). "Knockdown of METTL3 can suppress the proliferation, migration, and invasion of the human osteosarcoma cell lines SAOS-2 and MG63 by inhibiting the m6A methylation level and expression of the ATPase family AAA domain-containing protein 2 (ATAD2)." (PMID 34094986, 2021). "The transcriptome-wide m6A sequencing result of chemoresistant osteosarcoma stem cells revealed that over-expression of METTL3 and low METTL14 expression are associated with doxorubicin chemoresistance and stemness of osteosarcoma cells." (PMID 34094986, 2021). "METTL3 is perceived as an essential performer of m6A modifications in osteosarcoma (OS), bladder cancer (BCa), and cutaneous squamous cell carcinoma (cSCC), mediating the stemness properties of CSCs and tumor progression." (PMID 34586737, 2021). "METTL3 can promote osteosarcoma development by directly increasing the m6A methylation level and the expression of lymphoid enhancer-binding factor 1(LEF1), and by activating the Wnt/β-catenin signaling pathway." (PMID 34094986, 2021). "In osteosarcoma cells, m6A writers, including METTL3, METTL14, WTAP, and KIAA1429 are mostly present in the nucleus." (PMID 34094986, 2021). "METTL3 knockdown affected m6A methylation and impairs osteosarcoma cell proliferation and metastasis." (PMID 32709063, 2020). "The expression of METTL3 in human osteosarcoma tissue and osteosarcoma cell lines was found to be significantly upregulated, a characteristic that was related to osteosarcoma cell proliferation, migration, and invasion." (PMID 32398132, 2020). "Recently, METTL3 was shown to be localized in the cytoplasm and nuclei of osteosarcoma cells, where it acted as an oncoprotein." (PMID 32709063, 2020). "The m6A level in total RNA increased in osteosarcoma tissues and cell lines, and METTL3 promoted the cell proliferation, migration and invasion of osteosarcoma by modulating the m6A level of LEF1 and activating Wnt/β‐catenin." (PMID 33029866, 2020). "Potential therapeutic opportunities may arise by focusing on networks involving METTL3 and DNA‐PKcs, which could enhance the effectiveness of anlotinib and combat drug resistance in patients with osteosarcoma." (PMID 39924638, 2025). "Similarly, UZH1a, a well-characterized METTL3 inhibitor, suppresses the invasive and migratory capacities of multiple cancer cell types, including osteosarcoma and acute myeloid leukemia cells, through attenuation of m6A methylation." (PMID 40986143, 2025). "In addition, methyltransferase-like 3 (METTL3) is highly expressed in osteosarcoma cells, and the N6-methyladenosine (m6A) modification it participates in can act on the methylation sites of TGF-β1 mRNA, thus affecting related signaling pathways." (PMID 41035670, 2025). "Furthermore, silencing METTL3 inhibits proliferation and migration of osteosarcoma by regulating ATAD243." (PMID 37151889, 2023). "Methyltransferase-like 3 (METTL3), one of the m6A writers, is approved to play a role in the pathophysiology and growth of bone-related disorders including osteoporosis, arthritis, and osteosarcoma." (PMID 37215218, 2023). "For example, the roles of m6A and its methyltransferase METTL3 in osteosarcoma have been reported." (PMID 34647424, 2022).
osteosarcoma (continued). "Moreover, METTL3 promotes osteosarcoma cell progression by regulating the m6A level of LEF1 and activating the Wnt/β-catenin signaling pathway." (PMID 33490266, 2021). "METTL3/14 also plays an important role in modulating the chemoresistance of osteosarcoma." (PMID 34094986, 2021). "Thus, METTL3 promotes the growth of osteosarcoma cells by regulating the m6A level of LEF1 and activating the WNT/β-catenin signaling pathway." (PMID 32398132, 2020). "In addition, METTL3 promotes osteosarcoma cell progression by regulating the m6A level of LEF1 and activating the Wnt/β-catenin signaling pathway." (PMID 33033522, 2020). "Moreover, the ATPase family AAA domain-containing protein 2 (ATAD2), identified as the downstream target of METTL3, contributes to its oncogenic role in osteosarcoma." (PMID 32709063, 2020). "Additionally, we explored whether the m6A modification of PRKDC mRNA induced by METTL3 contributed to anlotinib resistance in osteosarcoma." (PMID 39924638, 2025). "Thus, targeting METTL3/PRKDC may be a novel strategy for improving therapeutic efficacy in human osteosarcoma." (PMID 39924638, 2025). "However, the relationship between METTL3 expression and anlotinib resistance in osteosarcoma remains unclear." (PMID 39924638, 2025). "Dose-dependent inhibition of METTL3 mRNA expression in the model of AML (MOLM-13 line) and osteosarcoma (U2OS line) cells." (PMID 41157107, 2025). "FISH‐IF co‐localisation assay confirmed similar distributions of METTL3 protein and PRKDC mRNA in MG63, U‐2 OS cells, and human osteosarcoma tissues." (PMID 39924638, 2025). "Altogether, these results confirm that YTHDF1 regulates METTL3‐mediated PRKDC m6A modification, contributing to the maintenance of anlotinib resistance in osteosarcoma." (PMID 39924638, 2025). "In osteosarcoma, Spautin-1–mediated inhibition of USP13 degrades METTL3, destabilizing ATG5 mRNA and impairing autophagy and glycolysis, which ultimately suppresses tumor growth." (PMID 40370434, 2025). "Elevated expression of METTL3 incurs an increase in the overall m6A modification level of the oncogene ZBTB7C mRNA, eventually promoting osteosarcoma progression." (PMID 40823087, 2025). "In osteosarcoma, knockdown of METTL3 decreases mRNA and protein levels of DRG1, which further leads to G2/M phase cell cycle arrest and inhibits osteosarcoma cell proliferation." (PMID 39289775, 2024). "Recent studies reported a positive association between the expression of methyltransferase-like 3 (METTL3) and MALAT1 in osteosarcoma patients." (PMID 38203269, 2023). "METTL3 and ALKBH5 expression levels are upregulated in doxorubicin-resistant osteosarcoma cells, while METTL14 expression is downregulated." (PMID 34094986, 2021). "METTL3 has also been found to facilitate the methylation of GTP-binding protein (DRG) 1, and thereby, promoting osteosarcoma growth, migration, and colony formation." (PMID 34094986, 2021). "METTL3 and METTL14 decrease the RNA level of tripartite motif 7 (TRIM7), while the upregulation of TRIM7 can increase metastasis and the chemoresistance of osteosarcoma by regulating ubiquitination of breast cancer metastasis suppressor 1 (BRMS1)." (PMID 34094986, 2021). "METTL3, an m6A methyltransferase, regulates the m6A level LEF1, promoting osteosarcoma progression." (PMID 39924638, 2025). "Several m6A genes, including METTL3, RBM15, IGF2BP3, and RNA-binding motif protein X (RBMX), were significantly upregulated in OS cell lines and OS tissues compared to osteoblast and non-osteosarcoma tissues." (PMID 40510136, 2025). "In addition, METTL3‐ and METTL14‐mediated m6A modifications of TRIM7 regulate osteosarcoma metastasis and chemoresistance." (PMID 39924638, 2025). "Furthermore, the increased METTL3 and ZBTB7C levels in human osteosarcoma tissues were confirmed, highlighting their potential as therapeutic targets and STM2457 as a promising drug." (PMID 40823087, 2025).
osteosarcoma (continued). "Specifically, METTL3-catalyzed m6A modification augments TGF-β1 transcript stability and translational efficiency by facilitating post-transcriptional mRNA processing, leading to increased secretion of TGF-β1 by osteosarcoma cells." (PMID 40986143, 2025). "Third, the role and mechanism of METTL3 in osteosarcoma were not further demonstrated in this study." (PMID 35156522, 2022). "Moreover, METTL3 can regulate the Wnt/β‐catenin signalling pathway and the m6A levels of LEF1, thus promoting osteosarcoma progression." (PMID 34647424, 2022). "METTL3, YTHDC1, and FTO were identified as key regulators, and the osteosarcoma prognostic signature based on these m6A regulator could prognostically stratify the patients independently of potential confounding factors." (PMID 34011074, 2021). "However, the role of METTL3 and small nucleolar RNA host gene 1 (SNHG1) playing in osteosarcoma (OS) remains largely unknown." (PMID 40510136, 2025). "Moreover, METTL3 promotes osteosarcoma progression by increasing the stability of DANCR mRNA through m6A modification, which means that METTL3 may be a promising therapeutic target for osteosarcoma treatment." (PMID 39015175, 2024). "Moreover, there was a significant decrease in demethylase ALKBH5 mRNA inversely correlated with m6A contents in all three osteosarcoma cell lines as compared with hOB cells, but not in METTL3, METTL14, WTAP, and FTO." (PMID 33431791, 2021). "To our knowledge, we are the first to report that osteosarcoma patients could be prognostically stratified using METTL3, YTHDC1, and FTO, which is independent of potential confounding factors including age, gender, and metastatic status." (PMID 34011074, 2021).
Obesity (56 papers, 2016 to 2025). Accumulation of substantial excess body fat. "Intermittent fasting to inhibit METTL3 activity and reduce m6A methylation levels attenuates apoptosis and lipid deposition and improves cardiac structure and function in obesity-associated cardiomyopathy." (PMID 41194259, 2025). "Collectively, these results indicate that multigenerational paternal obesity enhances the susceptibility of the offspring to spermatogenesis disorders by increasing METTL3-mediated Wt1 N6-methyladenosine modification." (PMID 38355624, 2024). "The enzymes involved in m6A RNA methylation, including methyltransferase‐like protein 3 and 14 (Mettl3, Mettl14), as well as demethylase, fat mass and obesity‐associated (FTO) were further examined." (PMID 39445711, 2024). "Many disease processes such as NASH, obesity, and diabetes have been found to be regulated by m6A RNA writer proteins such as methyltransferase like 3 (METTL3) and Wilm’s tumor 1–associating protein (WTAP) by altering m6A RNA modification or chromatin accessibility." (PMID 37777158, 2023). "We next determined whether BAT Mettl3 expression was associated with obesity by measuring BAT Mettl3 expression in two obese mice models (high-fat diet-induced obese (DIO) and leptin-deficient ob/ob mice)." (PMID 32245957, 2020). "Collectively, these results suggest that upregulation of adipocyte Mettl3, Mettl14, and m6A methylation of Atgl, Cgi‐58, Adrb2, and Adrb3 transcripts causes, at least in part, adipose catecholamine resistance, lipolysis suppression, adipose expansion, and metabolic disorders in obesity." (PMID 37526326, 2023). "Two SNP markers within the METTL3 gene correlate with BMI implying that genetic variability in METTL3 encoding the catalytic subunit of the m6A methyltransferase complex may influence clinical variables of obesity." (PMID 34950106, 2021). "Qin and colleagues further demonstrated that deleting METTL3 prevented inflammatory and metabolic phenotypes and ameliorated obesity in mice." (PMID 40066222, 2025). "On the other hand, in brown adipose tissue, which is essential for energy metabolism, specific knockout of METTL3 reduces m6A levels and suppresses key thermogenic genes, thereby exacerbating obesity and insulin resistance induced by a high-fat diet." (PMID 41446042, 2025). "Collectively, our data hint at the importance of m6A formation in the 3′ UTR of Fgf1 by METTL3 for the control of circulating FGF1 levels, suggesting regulation of factors implicated in diet-induced obesity." (PMID 40272887, 2025). "“Writers” like METTL3 and METTL14 add m6A marks, “erasers” such as fat mass and obesity-associated protein (FTO), ALKBH5 remove them, and “readers” including YTHDF1, YTHDC1 recognize the marks, mediating functional outcomes." (PMID 40442779, 2025). "Upregulation of METTL3 in myeloid cells also contributes to obesity by reducing the stability of DNA damage-inducible transcription 4 mRNA." (PMID 41194259, 2025). "In male mice subjected to a long-term diet-induced obesity model, Mettl3 mRNA expression is reduced." (PMID 40729009, 2025). "Participating in this mechanism are “writer” methyltransferases, such as methyltransferase-like 3 (METTL3) and Wilms tumor 1-associated protein (WTAP), and “eraser” demethylases, such as AlkB homolog H5 (ALKBH5) and fat mass and obesity (FTO)." (PMID 40284466, 2025). "Liver METTL14, METTL3, and m6A‐methylated G6pc mRNA are upregulated in mice with diet‐induced obesity." (PMID 40278833, 2025). "METTL3 has been reported to play a key role in the development of obesity which can drive lipid accumulation in a variety of cells by affecting lipid synthesis and catabolism." (PMID 41194259, 2025). "Emerging studies demonstrate that myeloid lineage–restricted deletion of METTL3 prevents obesity in mice with improved inflammatory and metabolic phenotypes." (PMID 40729009, 2025).